ALKBH5 (alkB homolog 5, RNA demethylase)
Diseases named in the same sentence as ALKBH5 in open-access papers (continued):
Sharing a sentence is not in itself a finding about the gene and the disease.
tumor (continued). "For instance, ALKBH5 regulated Tregs and MDSC accumulation via modulating the expression of Mct4/Slc16a3; FTO facilitated immune invasion and desensitized tumor cells to T cell cytotoxicity; YTHDF1 was correlated with immune cell infiltration but attenuated DCs' cross-presentation capacity." (PMID 35936362, 2022). "Similarly, the current study also confirmed that ALKBH5 knockdown increased mRNA stability, which increased TIMP3 protein expression and acted as a tumor suppressor in A549 cells." (PMID 35318440, 2022). "In summary, upregulated ALKBH5 plays an oncogenic role in HNSCC by inhibiting RIG-I-mediated IFNα secretion via the IKKε/TBK1/IRF3 pathway, which ultimately reduces immune-killing cell infiltration and promotes tumor progression." (PMID 35395767, 2022). "However, previous research on ALKBH5 in GBM reported that the deletion of ALKBH5 disrupted GBM stem-like cell tumorigenicity and inhibited tumor progression." (PMID 36566230, 2022). "The depletion of ALKBH5 contributed to reduced tumorigenesis with significantly lower tumor volumes and weights compared with the negative control group." (PMID 35982895, 2022). "Hypoxia-mediated ALKBH5 is reported to significantly accelerate TAM recruitment and immunosuppression and the m6A methyltransferase METTL14 in TAMs induces CD8+ T cell dysfunction and tumor progression." (PMID 35794625, 2022). "Notably, Alkbh5 modulates Mct4/Slc16a3 expression and lactate content of TME and the composition of myeloid-derived suppressor cells (MDSCs) and tumor-infiltrating Tregs." (PMID 35646923, 2022). "In this study, we found that ALKBH5 was significantly downregulated in tumor tissues compared to the adjacent tissues, and its expression was negatively correlated with SH3BP5-AS1 levels in tumor tissues." (PMID 36397058, 2022). "ALKHB5, SLC7A2, and CGB3 showed a similar tendency to inhibit tumor development, suggesting that SLC7A2 and CGB3 may also play a suppressor role in GC; the internal mechanism of how ALKBH5 regulates these genes needs to be further explored." (PMID 36686788, 2022). "The expression of ALKBH5 is not fully consistent across different tumours, which indicates the tissue‐specific expression of ALKBH5." (PMID 35979628, 2022). "Then, the expression of ALKBH5 in 86 pairs of LSCC and non‐tumour tissues was detected by qRT‐PCR." (PMID 34850551, 2022). "Therefore, we detected the mRNA expression levels of demethylation genes ALKBH5 and FTO between tumor stem-like cells and their matching cell lines." (PMID 35568876, 2022). "Inactivation of ALKBH5 causes an increase in m6A levels on mRNAs, and studies have shown that ALKBH5 is essential for the progression of non-neoplastic and neoplastic diseases of the reproductive, immune, circulatory, and nervous systems." (PMID 36212687, 2022). "In addition, BNIP3 promotes cancer through demethylation catalyzed by FTO, while ALKBH5 upregulates the expression of NANOG through demethylation of m6A and promotes the aggregation of breast cancer cells in the tumour microenvironment." (PMID 34794452, 2021). "However, despite of positive regulation of ALKBH5 on SLC25A28 and SLC25A37 observed here, we found that these two proteins were overexpressed in the tumor cells of PDAC." (PMID 34733841, 2021). "ALKBH5 and YTHDF1 could possibly play a potential role in the transformation of cold to hot tumor in COAD." (PMID 34079761, 2021). "ALKBH5 mRNA and protein levels were significantly increased in HCC tissues compared to peri-tumor." (PMID 34112124, 2021).
tumor (continued). "In addition, the abundances of circ_0072083, ALKBH5 and NANOG were evidently enhanced and miR-1252-5p expression was decreased in tumor tissues in U251/TR-sh-NC EXO + TMZ group, and these events were reversed in U251/TR-sh-circ_0072083 EXO + TMZ group." (PMID 33975615, 2021). "Tumor immune-related genes YTHDC1, YTHDC2 and ALKBH5 were found." (PMID 34737950, 2021). "Notably, the tumor tissue showed significantly higher expression levels of m6A regulators, except for FTO and ALKBH5, compared with the normal tissue with a P value <0.05." (PMID 33928026, 2021). "ALKBH5 was found to have the opposite function to METTL3, it could serve as a tumor suppressor gene in CRC by reducing the nuclear accumulation of RP11 and thus inhibiting the function of EMT." (PMID 33836813, 2021). "The mechanism is that ALKBH5 affects the efficacy of immunotherapy during immune checkpoint blockade by regulating the expression and lactate content of MCT4/Slc16a3 in TME and the composition of tumor-infiltrating T cells and myeloid suppressor cells." (PMID 34660577, 2021). "ALKBH5 demethylates Forkhead box M1 (FOXM1), which is one of the main tumor inducers." (PMID 33511112, 2020). "In addition, ALKBH5 promotes expression of NANOG, a well-known factor for the self-renewal process of undifferentiated ESCs, and thus it plays a role in primary tumor formation and metastasis." (PMID 31804607, 2020). "In addition, the protein expression levels of ALKBH5 and FTO in renal cancer tissues were significantly lower than those in normal kidney tissues and other tumor tissues." (PMID 32398132, 2020). "In addition, m6A demethylase ALKBH5 is directly upregulated by DDX3, RNA helicase, which plays an important role in cell proliferation, invasion, and metastases in several kinds of neoplasms." (PMID 33375464, 2020). "Thus, ALKBH5 has been suggested as a potential target for novel anticancer therapies, due to a direct correlation of its expression with primary HNSCC tumor size." (PMID 33375464, 2020). "In addition, researchers found low expression of lncRNA-GAS5-AS1 in cervical cancer cells; this lncRNA has been shown to interact with the tumor suppressor GAS5 and increase its stability by reducing ALKBH5-mediated m6A modification of GAS5 mRNA." (PMID 32398132, 2020). "Furthermore, the binding of NEAT1 and ALKBH5 can negatively affect the expression of EZH2, thereby promoting tumor cell invasion and metastasis." (PMID 33291485, 2020). "A previous study discovered that the “writers” of m6A methylation, METTL3 and METTL14, could play both oncogenic and tumor suppressor roles in numerous cancers, while oncogenic roles have been reported for “erasers” such as FTO and ALKBH5." (PMID 31722709, 2019). "In addition to ALKBH5, FTO is another m6A demethylase involved in tumor immunity." (PMID 41562066, 2025). "Another demethylase ALKBH5 increases the stability of the lncRNA KCNK15-AS1, inactivates the PI3K/AKT pathway, and upregulates Phosphatase and tensin homolog (PTEN) expression through a m6A-dependent mechanism, thereby preventing tumor cell proliferation and metastasis." (PMID 39904996, 2025). "Second, delivery optimization via antibody-drug conjugates (ADCs) could exploit tumor-specific antigens (e.g. HER2, TROP-2) to localize inhibitors (e.g. FTO or ALKBH5 inhibitors) to cancer cells, leveraging stable linkers and high drug-antibody ratios (DAR) to minimize off-target immune suppression." (PMID 40176140, 2025). "For example, ALKBH5-mediated changes in m6A modification may regulate the expression of Mct4/Slc16a3 and lactate content in the CRC microenvironment, as well as the composition of tumor-infiltrating Treg and myeloid-derived suppressor cells." (PMID 40958857, 2025).
tumor (continued). "Decreased expression of seven m6A regulators [METTL14, YTHDC2, FTO, ALKBH5, HNRNPA2B1, VIRMA, and RNA-binding motif protein, X chromosome (RBMX)] was evident in OC tissues sample and in the advanced-stage cohort, suggesting crucial roles in tumor suppressors of OC progression." (PMID 38544837, 2024). "The findings of the present study imply that ALKBH5 is a potential biomarker to predict the response of patients with NSCLC to anti PD-L1 immunotherapy, and that targeting ALKBH5 may be a promising strategy to enhance anti-tumor immunity." (PMID 38872221, 2024). "In addition, through subcutaneous tumorigenesis and IHC staining assays in nude mice, we found that downregulation of ARHGAP35 could reverse the inhibition of NPC tumor growth by promoting apoptosis in nude mice after combined knockout of FTO and ALKBH5." (PMID 38263362, 2024). "To evaluate whether ALKBH5 could regulate CD58, we first examined the protein level of ALKBH5 in GC cell lines and found that it was upregulated in GC cell lines compared with pooled non-tumor gastric tissues." (PMID 38589927, 2024). "At present, the relationship between ALKBH5 and radiosensitivity of tumours has not been reported." (PMID 36792369, 2023). "Moreover, in line with in vitro results, ALKBH5 over-expression led to the higher rate of tumor formation in subcutaneous xenograft models of QGP-1 cells, proved by the higher tumor weight and volume, which could also be rescued by FABP5 knockdown." (PMID 37858219, 2023). "Thus, we hypothesised that hypoxia-induced enhanced HIF-1α secretion also stimulated ALKBH5 expression and accelerated early lymphangiogenesis in EOC cells, thereby enhancing tumor metastasis." (PMID 36632222, 2023). "The baicalin hydrate inhibited tumor growth in NPC both in vivo and in vitro by influencing the genomic stability and affecting the splicing of Suv39H1 by upregulating m6A RNA methylation, as evidenced by increased METTL3 and METTL14 and decreased FTO and ALKBH5." (PMID 35164788, 2022). "However, most studies focused on the function of ALKBH5 within tumor cells, not the tumor microenvironment." (PMID 36566230, 2022). "For CHC patients, TERT and ALKBH5 are found to be integrated by HBV fragments in 4 tumors and 2 tumors respectively; interestingly, FN1 is also the only gene with HBV integration event occurred in more than 2 non-tumor samples, which is consistent with the results of ICC samples." (PMID 36123506, 2022). "In order to unravel the driving forces behind the markedly changed m6A patterns in the tumor adjacent tissues, we analyzed the expression of proteins related to coordinate m6A modifications by Western blot, including m6A methylation writers (METTL3, METT14) and erasers (FTO, ALKBH5)." (PMID 36172147, 2022). "Notably, we show here that upon ALKBH5 overexpression, the stabilized FBXL5 further elicited the downregulation of the IRP2 and SNAI1 proteins, both of which are substrates ubiquitinated by FBXL5 and are crucial drivers of tumor progression." (PMID 34733841, 2021). "Similarly, the miR-107/LAST2 axis is regulated by the m6A “eraser” ALKBH5 in an HuR-dependent manner to decrease YAP activity and inhibit tumour growth; lncRNA MALAT1 is stabilized by the METTL3/YTHDF1 complex and its RNA level is increased with high levels of m6A modification." (PMID 35004679, 2021). "Therefore, the expression levels of 7 m6A regulators (METTL14, YTHDC2, FTO, ALKBH5, HNRNPA2B1, VIRMA, and RBMX) were lower in both the OC tissues and the high-stage group, indicating their potential function as tumor suppressors in OC tumorigenesis and development." (PMID 34631700, 2021). "Most increased regulators in tumor cases compared to normal cases were YTHDF2 (p < 0.001), FTO (p < 0.001), YTHDC1 (p < 0.001), YTHDC2 (p < 0.001), YTHDF1 (p < 0.001), KIAA1429 (p < 0.001), METTL3 (p < 0.010), WTAP (p < 0.001), RBM15 (p < 0.001), HNRNPC (p < 0.001), and ALKBH5 (p = 0.001)." (PMID 32733931, 2020).
tumor (continued). "However, the mechanism through which ALKBH5 regulates NSCLC tumor growth and metastasis is not clear." (PMID 32106857, 2020). "Furthermore, by referring to the information collected on patients’ clinicopathological characteristics, our immunohistochemistry stanning results proved that low expression of ALKBH5 significantly affected TNM stage, tumour differentiation, and vascular invasion of PC." (PMID 32429928, 2020). "In addition, we wonder whether dysregulation of FTO or ALKBH5 exists in CRC and contributes to tumor formation or progression." (PMID 32111213, 2020). "In contrast, the expression of WTAP, FTO, or ALKBH5 was not significantly altered in tumor tissues." (PMID 32175271, 2020). "Moreover, hypoxia and high ALKBH5 levels restore the stem-like state of differentiated ECSCs and increase the ECSC-like phenotype, whereas the knockdown of HIFs or ALKBH5 significantly reduces their tumour initiation capacity." (PMID 32913192, 2020). "In conclusion, this study identified a negative correlation between ALKBH5 and YAP expression, an interaction that contributes to regulating NSCLC tumor growth and metastasis." (PMID 41216500, 2026). "We compared the protein levels of HSPA4, ALKBH5 and CD58 in tumor tissues between responders and non-responders by using mfIHC." (PMID 38589927, 2024). "Increased HSPA4 (P < 0.01), ALKBH5 (P < 0.05) and decreased CD58 (P < 0.05) were observed in tumor tissues of responders compared with non-responders." (PMID 38589927, 2024). "The analysis indicated that, in comparison to the Normal group, the Tumor group's expression of METTL3 was considerably up-regulated, that of FTO was down-regulated, and those of METTL14 and ALKBH5 were not significantly affected." (PMID 37828232, 2023). "By performing online database searching of the GEPIA database, although FTO and ALKBH5 present no obvious difference between tumor and adjacent tissue, METLL3 significantly decreased in tumor tissues compared with adjacent tissues." (PMID 35530319, 2022). "To investigate m6A eraser expression in CRC, we first analyzed FTO and ALKBH5 mRNA and protein levels in paired CRC tumor and adjacent normal tissues from Sun Yat-sen University Cancer Center (SYSUCC)." (PMID 34218271, 2021). "Our findings illustrated that ALKBH5 and YTHDF1 have potential in tumor immunity and provided novel insights into the relationship between m6A modification and immunity." (PMID 34079761, 2021). "Collectively, our results demonstrate that the non-metabolic activity of 6PGD regulates ALKBH5 and promotes global m6A modification in CRC, adding another dimension to the regulation of CRC tumor growth and metastasis through the MDM2-CCNA2/HMGA2 axis in a non-metabolic manner." (PMID 40611205, 2025). "Notably, the expression of ALKBH5 or HIF1α was increased in PC tissues, while the expression of HDAC4 was not significantly different between normal and tumor tissues." (PMID 37149664, 2023). "Interestingly, ALKBH5−/− TBM showed prolonged survival and slower tumor growth as compared to the non-transfected (NTC) control mice, suggesting the direct involvement of ‘ALKBH5’ in interfering with the efficacy of anti-PD-1 antibody." (PMID 34571899, 2021). "However, the mechanism whereby ALKBH5 regulates YAP expression and activity to inhibit NSCLC tumor growth and metastasis is not clear." (PMID 32106857, 2020). "The oncogenic or tumor-suppressive feature of demethylases may not be determined by overall m6A levels, but rather by m6A dynamics on specific key target genes driving leukemogenesis, such as ELK3, which is evidently not a shared target with ALKBH5." (PMID 40435251, 2025). "The compared with adjacent non-tumorous tissues, we found a higher level of RBM15, IGFBP1, RBMX, FTO, and ALKBH5 in all five STAD tissues, RBM15, FTO and ALKBH5 were overexpressed in STAD tumor tissues, while the expression of IGFBP1, RBMX was not changed in STAD tumor tissues." (PMID 37019148, 2023).
tumor (continued). "However, tumor-promoting effects of ALKBH5 existed across our MM cell lines with various genetic characteristics, including RPMI-8226 that had no IgH translocation but displayed the highest ALKBH5 expression." (PMID 34759347, 2022). "Moreover, the study was performed based on TCGA and GEO; we could not illustrate the expression of ALKBH5 and YTHDF1 from the protein level or demonstrate the direct mechanisms of ALKBH5/YTHDF1 in anti-tumor immunity." (PMID 34079761, 2021).